FAM234A (family with sequence similarity 234 member A)
Synonyms: C16orf9; ITFG3; DKFZP761D0211; FLJ32603; gs19
Tractability: Antibody: UniProt predicts a signal peptide or a membrane-spanning region. PROTAC: ubiquitination databases record sites on it; its protein half-life has been measured.
Gene: Protein-coding gene on chromosome 16 (234,521 to 272,183, forward strand). Ensembl gene ENSG00000167930.
Subcellular location: Membrane
Subcellular location (Human Protein Atlas): Mitochondria; Nucleoplasm
Gene Ontology:
Molecular function: protein binding
Cellular component: cell surface; extracellular exosome; membrane
Genetic constraint (gnomAD): Loss-of-function variants: 38 observed, 44.47 expected, observed/expected ratio (o/e) 0.85, 90% interval 0.66 to 1.12. The upper end of that interval is the gene's LOEUF score, 1.12, which puts it in group 4 of 6, group 1 being the genes least tolerant of losing a copy. Missense variants: 759 observed, 712.14 expected, observed/expected ratio (o/e) 1.07, 90% interval 1 to 1.13. Synonymous variants: 347 observed, 306.74 expected, observed/expected ratio (o/e) 1.13, 90% interval 1.03 to 1.24.
Homologues: Orthologues: chimpanzee FAM234A (99% identical), macaque FAM234A (95% identical), guinea pig FAM234A (75% identical), mouse Fam234a (74% identical), rat Fam234a (72% identical), dog FAM234A (72% identical), rabbit FAM234A (71% identical), pig FAM234A (69% identical), tropical clawed frog fam234a (42% identical), zebrafish fam234a (30% identical), Drosophila melanogaster CG6184 (22% identical), Drosophila melanogaster CG3618 (16% identical). Paralogues in human: FAM234B (24% identical).
Diseases named in the same sentence as FAM234A in open-access papers:
FAM234A is named in the same sentence as 7 diseases in open-access papers, as found by Europe PMC text mining. Sharing a sentence is not in itself a finding about the gene and the disease. The quoted sentences say what the papers report.
asthma (1 paper, 2021). "We discovered several risk-increasing associations with traits related to liver disease, eye disease and cancer, among others, as well as risk-lowering associations for hypertension (SLC9A3R2), diabetes (MAP3K15, FAM234A) and asthma (SLC27A3)." (PMID 34662886, 2021).
diabetes (1 paper, 2021). "Collectively, results from both rare and common variants implicate FAM234A, a gene of unknown function, in the aetiology of diabetes." (PMID 34662886, 2021).
FAM234A also shares sentences with these, for which no sentence is quoted: cancer (2 papers); Hypertension (1); liver disease (1); type-2 diabetes (1); α-thalassemia (1).